ZEB1 (zinc finger E-box binding homeobox 1)
Diseases named in the same sentence as ZEB1 in open-access papers (continued):
Sharing a sentence is not in itself a finding about the gene and the disease.
cancer (continued). "Since reciprocal repression of miR-200c and ZEB1 promotes EMT in several types of cancer cell, we hypothesized that CD44s first suppresses expression of miR-200c in SAS-3.4 cells, thereby up-regulating ZEB1." (PMID 29515788, 2018). "Thus, ZEB1 represses several genes in carcinomas, but also activates transcription, when pairing with the co‐activator YAP of the Hippo pathway, inducing mesenchymal gene expression." (PMID 29744893, 2018). "MZF1, SOX10 and ZEB1 shRNAs displayed strong effect on survival of cancer cells." (PMID 28423538, 2017). "The rescue of Ngn3 expression attenuated ZEB1-induced cancer stemness and symmetric CSC division." (PMID 28903350, 2017). "ZEB1 turns into a transcriptional activator by interacting with YAP1 in aggressive cancer types." (PMID 28953220, 2017). "ZEB1 has been shown to carry out both repressive and active functions in cancer." (PMID 28246407, 2017). "Moreover, as an oncogenic lncRNA in multiple cancers, H19 functioned as miRNA sponge to lead to the de-repression of ZEB1 and ZEB2 genes in the mesenchymal cells." (PMID 29340065, 2017). "As HAS2 expression and HAS2-generated HA have been shown to promote tumorigenesis, we asked whether HAS2 activity induces ZEB1 expression in cancer cells." (PMID 28086235, 2017). "Intriguingly, ZEB1 expression was dramatically suppressed in ERK1 or 2-knockdown cancer cells with stimulation of GM-CSF, suggesting that ZEB1 may represent a key factor to mediate EMT program following GM-CSF stimulation." (PMID 28811578, 2017). "Therefore, it is not surprising that the main consequence of the ectopic expression of ZEB1 differs greatly between cancer cell types." (PMID 28618162, 2017). "Formalin-fixed, paraffin-embedded surgical specimens obtained from seven pretreated DSRCT patients were interrogated using GEP complemented by immunohistochemistry, a cancer stem cell array, and miRNA in situ hybridisation, including the combined chimera modules miRNA-200/ZEB1 and miRNA-34/SLUG." (PMID 28415643, 2017). "For further analyses, since ZEB1 is one of the major transcription factors that promote EMT in various cancer cells, we depleted ZEB1 in ES-2 and SKOV3 cells and examined the expression of E-cadherin as an epithelial marker, and vimentin and N-cadherin as mesenchymal markers." (PMID 29245917, 2017). "Additionally, when knocking down the expression of ZEB1 in 4T1 cells, the invasive ability of cancer cells was similar with IL-6 signal inhibition." (PMID 29383101, 2017). "Besides, we demonstrated that HOXA9 is essential for the expression of the zinc finger protein ZEB1, a master regulator of cancer metastasis." (PMID 28969042, 2017). "Furthermore, knockdown of ERK1/2 or ZEB1 attenuated chemoresistant potentials of GM-CSF-educated cancer cells." (PMID 28811578, 2017). "Most insights into its action would suggest that ZEB1 expression would be associated with a negative outcome in cancer patients based on its role in increasing tumorigenicity and stemness." (PMID 28246407, 2017). "Gene expression analyses comparing aggressive cancer cells with high ZEB1 levels of different entities (breast, pancreas, colon) and corresponding ZEB1 knockdown cells revealed a strong reprogramming with expression changes (>3-fold up or down) in thousands of genes." (PMID 26876920, 2016). "ZEB1 is known as an activator of EMT by transcriptionally suppressing E-cadherin expression, which not only promotes migration and invasion, but also is closely associated with the resistance to cancer chemotherapeutics in various cancer cells." (PMID 26883469, 2016). "The feedback loop of transcription factors ZEB1/2 repressing transcription of miR-200 family members, which in turn inhibit translation of ZEB1/2 on post-transcriptional level regulates epithelial to mesenchymal transition, a process important for cancer progression and metastasis." (PMID 27588394, 2016).
cancer (continued). "In contrast, cancers exhibiting little ZEB1 showed diminished VEGFA expression and vascularization." (PMID 26882471, 2016). "ZEB1 and ZEB2, has been demonstrated implicated in many cancers as EMT Key factors." (PMID 27861158, 2016). "Importantly, the bivalent state of the ZEB1 promoter defined cell populations that were able to convert from non-cancer stem cell to cancer stem cell states as a result of their ability to resolve the ZEB1 locus into an activate chromatin configuration." (PMID 27528222, 2016). "Interestingly, levels of both RAB25 and ESRP1 mRNA were high when ZEB1 mRNA levels were low and vice versa, which is consistent with a previous report examining other cancers." (PMID 26646320, 2016). "However, the remaining 40% of the genes were downregulated upon knockdown, indicating that their expression directly or indirectly (for example, through upregulation of miR-200) depends on the aberrant expression of ZEB1 in cancer cells." (PMID 26876920, 2016). "Additionally, Sundararajan and coworkers recently showed, in a cell line panel representing nine different cancer entities, that miR200c expression was high only in epithelial cells, whereas ZEB1 expression was high in mesenchymal cell types." (PMID 27941621, 2016). "Furthermore, CYT-Rx20 treatment had an inhibitory effect on cancer cell migration and invasion through activation of epithelial maker (ZO-1) and inactivation of mesenchymal markers (N-cadherin, ZEB1, Slug, Snail)." (PMID 27875549, 2016). "Thus, the ZEB1 pathway affects expression of a variety of genes that play important roles in drug resistance during cancer treatment." (PMID 26646320, 2016). "Taken together, our findings suggest that hTERT can promote cancer metastasis by stimulating EMT through the ZEB1 pathway and therefore inhibiting them may prevent cancer progression." (PMID 26540342, 2016). "We wanted to further investigate ZEB1-dependent mechanisms resulting in aggressive cancer types." (PMID 26876920, 2016). "Thus the detection of a common ZEB1/YAP target gene set points to a new mechanism how ZEB1 drives malignant cancer progression, towards invasion, metastasis and therapy resistance." (PMID 26876920, 2016). "Furthermore, although ZEB1 can be critical in the cell plasticity generating cancer stem cells, we have yet to study the relationship between EPB41L5 expression and the generation of cancer stem-like cells." (PMID 27617643, 2016). "Of note, STAT3 signaling is not only important for cancer cells in antagonizing apoptosis but has also been reported to be associated with cancer EMT by STAT3 transcriptional activation of EMT inducers TWIST1 and ZEB1 involved in E-cadherin repression." (PMID 27580057, 2016). "In addition, OVOL1/2 is highly correlated with GRHL2 and CDH3 (positively) and with ZEB1 (negatively) in a panel of 877 cell lines from The Cancer Cell Line Encyclopedia (CCLE)." (PMID 27008704, 2016). "Moreover, invasive phenotypes and stemness properties can be uncoupled in carcinomas, since ZEB1 and TWIST1 exhibit a dose‐dependent role in malignant progression." (PMID 27596438, 2016). "Previously, ZEB1 has been suggested to be the primary EMT mediator in multiple cancer types." (PMID 25868853, 2015). "ZEB1, a pro-metastatic transcription factor, is involved in cancer progression and metastasis." (PMID 26057751, 2015). "ZEB1, GB hypomethylated, is also highlighted as a central node in this cancer-related network." (PMID 26683690, 2015). "Furthermore, AKT knockdown prevented S100P-mediated ZEB1 upregulation in CL1-0 cells, suggesting that the FAK/AKT/ZEB1 axis plays a role in S100P-mediated cancer EMT and migration." (PMID 26320193, 2015). "Hence, due to the similar abilities of HIF-1α and ZEB1 to induce EMT and the overlapping phenotypes of HIF-1α and ZEB1 in null mice, it is likely that these two genes are located in the same pathway to regulate cancer metastasis." (PMID 26057751, 2015).
cancer (continued). "Besides ZEB1, several candidate targets of miR-429 were also identified essential for invasion and metastasis in cancer models." (PMID 25405387, 2015). "Therefore, here we explored a new molecular mechanism for HIF-1α contributing to EMT and cancer metastasis through binding to ZEB1." (PMID 26057751, 2015). "Altogether, these data suggest that activation of ZEB1 through the PI3K/AKT pathway might represent a general mechanism in LPA-induced cancer cell invasion and metastasis." (PMID 26098771, 2015). "We could show that MYLK and TKS5 are indeed direct mir-200c target genes, which expression patterns correlate positively with that of ZEB1 in different datasets of cancer cell lines." (PMID 26334100, 2015). "In addition, ZEB1 protein induces cell migration during development and cancer progression by repressing expression of E-cadherin in epithelial cells." (PMID 24763497, 2014). "In human gastric cell lines, treatment with ZEB1 siRNA could effectively abrogate the mobility of cancer cells." (PMID 25197668, 2014). "As a consequence, important cancer-related pathways are regulated, including Wnt- and Notch signaling, EMT associated genes (e.g., ZEB1/2, vimentin) and PTEN, contributing to IF-mediated inhibition of proliferation, invasion, migration and induction of apoptosis." (PMID 25322458, 2014). "However, these transcription factors also regulate many other genes involved in cancer stemness, invasion and metastasis; for example, ZEB1 represses miR-200 and Twist transactivates miR-10b." (PMID 24586203, 2014). "Previous data indicate that ZEB1 has emerged as a key player in cancer progression." (PMID 23420790, 2013). "Expression of ZEB1 has been observed in chemoresistant cells in cancers outside the CNS, but whether this relation is correlative or causative is thus far unknown." (PMID 23818228, 2013). "Furthermore, we describe a critical role for the OVOLs as regulators of cancer cell metastasis, by repressing ZEB1 and inducing ESRP1." (PMID 24124593, 2013). "Thus, Zeb1 proteins employ several evolutionary conserved mechanisms to regulate cell-cell adhesion during development and cancer." (PMID 23667256, 2013). "This regulation may characterize the great majority of cancer cells, as demonstrated by the high correlation between the OVOL-TFs, ESRP1 and E-cad in addition to their inverse correlation with ZEB1 and vimentin in 917 cancer cell lines." (PMID 24124593, 2013). "So far ZEB1 has been studied rather in the context of cancer than that of infection." (PMID 23565224, 2013). "In both human cancer cell lines knockdown of ZEB1 resulted in elevated EPCAM and CDH1 expression." (PMID 23667256, 2013). "Studies in human cancer cell lines revealed that ZEB1 and the miR-200 family are linked in a reciprocal negative feedback loop." (PMID 23667256, 2013). "Nonetheless, this result suggests that Zeb1 may be involved in IL-1β-mediated reactivation or de novo induction of cancer stem cells." (PMID 23174018, 2012). "Interestingly, however, grade III tumors showed less stromal zeb1 positivity than grade II carcinomas (p = 0.001)." (PMID 21324165, 2011). "Interestingly, the anti-anoikis and anti-metastatic effect of adenovirus E1a led to the discovery of the direct transcriptional repression of E-Cadherin by ZEB1 in human cancer cells." (PMID 24281177, 2010). "Recently, several other groups have reported a role for the miR-200 family in the Epithelial-Mesenchymal-transition (EMT) and in cancer cell migration, the latter by directly targeting the transcription factors ZEB1 and ZEB2, which regulate E-Cadherin, a mediator of cell-cell adhesion." (PMID 20420713, 2010). "However, we show that increase of miR-200c or direct knockdown of ZEB1 results in decreased proliferation in three different types of cancer cells." (PMID 20049172, 2010). "However, we and others have shown that in high grade, aggressive carcinomas that have undergone EMT, ZEB1 can be expressed, leading to loss of E-cadherin." (PMID 20049172, 2010).
cancer (continued). "In cancers or fibrosis, this feedback loop may be disrupted, leading to unregulated expression of ZEB1 or ZEB2." (PMID 20025777, 2009). "In order to determine transcription factors in cancer-associated fibroblast activation, which play a role in cell proliferation and cancer progression, we evaluated the expression of several transcription factors, including SOX9, POU5F1, ZEB1, JUN, and FOS in the HRTPT cell line exposed to arsenite." (PMID 40699854, 2025). "Zinc Finger E‐box Binding Homeobox 1 (ZEB1) and zinc fingers and homeoboxes 3 (ZHX3) have been extensively implicated in promoting epithelial‐mesenchymal transition (EMT), enhancing tumor cell migration and invasion, and thereby contributing to cancer aggressiveness and poor prognosis." (PMID 41020579, 2025). "Indeed, Snail and Zeb1 induced cell malignancy and a cancer stem cell phenotype in prostate cells." (PMID 40806166, 2025). "Therefore, miRNAs and ZEB1 closely interact to regulate cancer metastasis." (PMID 38733529, 2024). "Furthermore, ZEB1 is essential for the development of the pulmonary mesenchymal cancer phenotype." (PMID 39770330, 2024). "In addition, ZEB1 was involved in proliferation, migration and glycolysis of cancer cells." (PMID 38481182, 2024). "Thus, high expression level of ZEB1 is correlated with a poor outcome in cancer patients." (PMID 38773406, 2024). "In addition, according to the latest research, inactivation of ZEB1 may offer alternative approaches for cancer therapy with minimal side effects." (PMID 38183060, 2024). "Besides its role in EMT, ZEB1 may also promote (cancer) cell stemness and cancer therapy resistance." (PMID 38139138, 2023). "Knocking down Zeb1 as a mode of overcoming anoikis resistance and improving therapeutic response provides promise, wherein silencing Zeb1 in PCa cell lines leads to decreased cancer stem cell markers (CD44, CD133 and SOX2) and decreased ability to form protospheres and colonies." (PMID 37091854, 2023). "In support of this hypothesis, a previous study has revealed that ZEB1, a transcription factor that enhanced cancer metastasis by inducing EMT, promoted the sensitivity of cancer cells to ferroptosis inducers targeting GPX4 via regulating cellular lipid metabolism." (PMID 37311754, 2023). "In addition to its role in EMT and cancer progression, an increasing body of evidence suggests that ZEB1 might also be a determinant of (cancer) cell stemness." (PMID 38139138, 2023). "In addition to its critical role in the EMT process, the transcription factor ZEB1 might also be a determinant of (cancer) cell stemness and cancer therapy resistance." (PMID 38139138, 2023). "EMT in cancer is generally marked by transcriptional downregulation of epithelial markers, including E-cadherin, and upregulation of mesenchymal markers, including N-cadherin and vimentin, via activity of the transcription factors, including Twist-1, Snail, and ZEB1." (PMID 37046830, 2023). "The transcription factors SNAIL, SLUG, and ZEB1 are key regulators of EMT by modulating the expression levels of E-cadherin, N-cadherin, vimentin, and other proteins, and their increased expression is associated with poor outcomes and aggressive disease in many types of cancer." (PMID 37508550, 2023). "Therefore, ZEB1 turnover has been assessed in several cancers through cycloheximide chase assays." (PMID 35454770, 2022). "Furthermore, the expression of typical EMT-inducible transcription factors such as Snail1/2, Slug, ZEB1 (Zinc Finger E-box-binding Homeobox 1), and Twist in various cancers is driven by YAP, suggesting that the hippo pathway is involved in the activation of the EMT program." (PMID 36358270, 2022). "We subsequently investigated whether ZEB1 affects cancer stemness genes in OCM1." (PMID 35404029, 2022).
cancer (continued). "Moreover, the roles of EMT-TFs could be tissue-specific, as demonstrated by the different roles of SNAIL and ZEB1/2 in distant metastasis of various cancers." (PMID 36140527, 2022). "In addition, ZEB1 may directly bind and thereby regulate the expression of multiple cancer stem cell markers including MYC and ABCB1." (PMID 35404029, 2022). "Furthermore, the overexpression of FOXM1 leads to the acquisition of an EMT phenotype by activating the mesenchymal cell markers ZEB1, ZEB2, Snail2, E-cadherin, and vimentin, which are associated with increased spheroid-forming capacity and cancer stem cell surface markers (CD44 and EpCAM)." (PMID 36613925, 2022). "Besides, highly expressed ZEB1 plays an important role in cancer transformation and EMT." (PMID 36210463, 2022). "In addition, ZEB1 is well-known to be involved in the regulation of EMT in cancer cells." (PMID 35101080, 2022). "However, the function of Snail and ZEB1/2 during cancer progression is still controversial." (PMID 35451213, 2022). "Furthermore, the review will enhance the development of treatment strategies by identifying knowledge gaps in ZEB1′s regulatory mechanisms that could potentially be targeted to prevent and treat metastasis in cancer patients." (PMID 35454770, 2022). "Thus, when ESRP1/2 are downregulated by ZEB1/2, cancer cells express CD44s alone." (PMID 36140527, 2022). "Importantly, ZEB1 is crucial regulator in the tumorigenesis and cancer progression of HCC." (PMID 35468721, 2022). "Furthermore, it has been shown that ZEB1 may induce cancer stem cell features in various cancers and silencing of Zeb1 decreases treatment resistance and stem cell-like characteristics in Pca." (PMID 37305018, 2022). "Additionally, the cancer cell proliferation was markedly suppressed by si-ZEB1." (PMID 35798695, 2022). "Similarly, miR-484 plays both ani- and pro-cancer role depending on the types, and it attenuates the epithelial to mesenchymal transition of cervical cancer by targeting ZEB1 and SMAD2, metastasis by targeting MMP14 and HNF1A, and is usually downregulated in gastric cancer." (PMID 33435549, 2021). "These regulatory RNAs included the anti-sense RNAs HLA-F, LIFR, PRKAR2A, ZEB1, and long intergenic non-coding RNAs (LINC) 887, 1431, 2482, as well as microRNAs (MIRs) 22HG and 3648, which are associated with viral inflammation and cancer and cellular proliferation, respectively." (PMID 33763387, 2021). "Moreover, elevated expression of ZEB1 seems to predict worse overall survival in cancer patients." (PMID 33897890, 2021). "Likewise, Zeb1 siRNA markedly inhibited RCP-induced cancer cell migration." (PMID 32728068, 2020). "In addition to DUBs, other factors, such as CSN5, an oncogene involved in various types of cancer, may also interrupt the degradation of ZEB1 by stabilizing ZEB1 by directly interacting with it." (PMID 32014049, 2020). "Therefore, ZEB1 was considered to be a cancer-promoting factor in many cancers." (PMID 32694942, 2020). "Recent studies have shown that the suppression of the miR-200 family by ZEB1 results in the upregulation of programmed cell death protein 1 (PD-L1), which is related to the immune system, suggesting that the ZEB1/miR-200 axis could influence the immune recognition of cancer cells." (PMID 32014049, 2020). "DAXX/ZEB-1 pathway could be a potential therapeutic target for preventing cancer metastasis in CRC." (PMID 31942198, 2020). "Hence, effective anti-ZEB1 immunotherapy might serve as a promising tool for the reduction of cancer cell dissemination and metastasis and thus could help to eradicate various types of cancer." (PMID 32266287, 2020). "Therefore, inhibition of hsa-circ-005748 may in turn increase miR-200c expression to suppress ZEB1 and cancer metastasis." (PMID 32664703, 2020). "Nevertheless, unknown regulations regarding ZEB1 in cancer activity have yet to be elucidated." (PMID 33097763, 2020).